OXCT1 (3-oxoacid CoA-transferase 1)
Description:
Key enzyme for ketone body catabolism. Catalyzes the first, rate-limiting step of ketone body utilization in extrahepatic tissues, by transferring coenzyme A (CoA) from a donor thiolester species (succinyl-CoA) to an acceptor carboxylate (acetoacetate), and produces acetoacetyl-CoA. Acetoacetyl-CoA is further metabolized by acetoacetyl-CoA thiolase into two acetyl-CoA molecules which enter the citric acid cycle for energy production. Forms a dimeric enzyme where both of the subunits are able to form enzyme-CoA thiolester intermediates, but only one subunit is competent to transfer the CoA moiety to the acceptor carboxylate (3-oxo acid) and produce a new acyl-CoA. Formation of the enzyme-CoA intermediate proceeds via an unstable anhydride species formed between the carboxylate groups of the enzyme and substrate (By similarity).
Synonyms: SCOT; OXCT
Tractability: Small molecule: it has a binding pocket of medium quality. PROTAC: ubiquitination databases record sites on it; its protein half-life has been measured.
Gene: Protein-coding gene on chromosome 5 (41,730,064 to 41,870,589, reverse strand). Ensembl gene ENSG00000083720.
Subcellular location: Mitochondrion
Subcellular location (Human Protein Atlas): Mitochondria
Pathways (Reactome):
Metabolism: Utilization of Ketone Bodies
Metabolism of proteins: Mitochondrial protein degradation
Gene Ontology:
Molecular function: succinyl-CoA:3-oxo-acid CoA-transferase activity; CoA-transferase activity; identical protein binding
Biological process: ketone body catabolic process; adipose tissue development; heart development; positive regulation of insulin secretion involved in cellular response to glucose stimulus; response to activity; response to ethanol; response to hormone; response to nutrient; response to starvation; response to xenobiotic stimulus
Cellular component: mitochondrion; mitochondrial matrix
Genetic constraint (gnomAD): Loss-of-function variants: 9 observed, 30.16 expected, observed/expected ratio (o/e) 0.3, 90% interval 0.18 to 0.52. The upper end of that interval is the gene's LOEUF score, 0.52, which puts it in group 2 of 6, group 1 being the genes least tolerant of losing a copy. Missense variants: 237 observed, 361.82 expected, observed/expected ratio (o/e) 0.66, 90% interval 0.59 to 0.73. Synonymous variants: 112 observed, 131.96 expected, observed/expected ratio (o/e) 0.85, 90% interval 0.73 to 0.99.
Gene-disease validity (ClinGen):
ClinGen rates the evidence that OXCT1 causes each of these diseases.
mitochondrial disease (autosomal recessive): Definitive.
Homologues: Orthologues: macaque OXCT1 (96% identical), chimpanzee OXCT1 (94% identical), rabbit OXCT1 (94% identical), guinea pig OXCT1 (93% identical), mouse Oxct1 (92% identical), rat Oxct1 (92% identical), dog OXCT1 (91% identical), pig OXCT1 (80% identical), zebrafish oxct1a (78% identical), tropical clawed frog oxct1 (77% identical), zebrafish oxct1b (75% identical), Caenorhabditis elegans C05C10.3 (61% identical), and 1 more. Paralogues in human: OXCT2 (74% identical).
Diseases named in the same sentence as OXCT1 in open-access papers:
OXCT1 is named in the same sentence as 66 diseases in open-access papers, as found by Europe PMC text mining. Sharing a sentence is not in itself a finding about the gene and the disease. The quoted sentences say what the papers report.
hepatocellular carcinoma (10 papers, 2016 to 2026). A malignant tumor that arises from hepatocytes. "In hepatocellular carcinoma, TAMs highly express 3-oxoacid CoA-transferase 1 (OXCT1), promoting the formation of ketone metabolism by-product succinate, which promotes H3K4me3 at the upstream promoter of Arg1." (PMID 40055311, 2025). "In glioblastoma, KAT2A/α-KGDH complex-driven histone H3 succinylation at K79 activates oncogenic transcription, while in hepatocellular carcinoma, OXCT1-succinylated LACTB reinforces mitochondrial metabolism to support tumor progression." (PMID 41383634, 2025). "In contrast, serum starvation in hepatocellular carcinoma (HCC) cells increases OXCT1 expression through activation of the mTORC2-Akt-SP1 pathway." (PMID 36432618, 2022). "In hepatocellular carcinoma (HCC), OXCT1 functions as a lysine Succinyl transferase, modifying LACTB at lysine 284 to enhance mitochondrial membrane potential and support tumor growth." (PMID 40931345, 2025). "In human hepatocellular carcinoma (HCC), tumor cells overexpress OXCT1 when nutrient-deprived, suggesting that these cells, contrary to the normal hepatocytes counter-part which synthesize and produce KB, catabolize β-OHB when they are nutrient stressed." (PMID 29725585, 2018). "Under serum-starved conditions, hepatoma cells are able to express BDH1 and 3-oxoacid CoA-transferase 1 (OXCT1) as well as oxidize ketones." (PMID 36077764, 2022).
breast carcinoma (6 papers, 2017 to 2026). "For example, recombinant transduction of human breast cancer cells (MDA-MB-231) with either OXCT1 or ACAT1 is indeed sufficient to metabolically promote tumor growth and metastasis, in pre-clinical models." (PMID 29108233, 2017). "Importantly, over-expression of OXCT1 or ACAT1 in human breast cancer cells is sufficient to genetically drive tumorigenesis and/or lung metastasis, validating that they indeed behave as metabolic “tumor promoters”." (PMID 29108233, 2017). "In further support of this “metabolic-coupling” hypothesis, recombinant over-expression of ACAT1 or OXCT1 in MDA-MB-231 breast cancer cells was indeed sufficient to promote tumor growth and lung metastasis." (PMID 29108233, 2017).
glioma (6 papers, 2011 to 2024). A benign or malignant brain and spinal cord tumor that arises from glial cells (astrocytes, oligodendrocytes, ependymal cells). "Five genes associated with the prognosis of glioma (ECI2, MCCC2, OXCT1, SUCLG2, and CPT2) were revealed and then, validated using glioma tissues, providing novel insights into individualized treatment and prognosis." (PMID 39491527, 2024). "3‐oxoacid CoA‐transferase 1 (OXCT1) promotes glycolysis by catalyzing the breakdown of ketone bodies, thereby contributing to the proliferation of glioma cells." (PMID 39491527, 2024). "This study revealed five genes associated with the prognosis of glioma (ECI2, MCCC2, OXCT1, SUCLG2, and CPT2), providing novel insights into individualized treatment and prognosis." (PMID 39491527, 2024). "In a recent clinical trial, differential expression of ketolytic enzymes (including BDH1 and OXCT1) was described in gliomas." (PMID 31399389, 2020). "Similar to tumors of peripheral tissues, glial tumors were found to have less activity of 3-oxoacid-CoA transferase 1 (OXCT1), the rate-limiting enzyme of ketone body degradation, than normal human white (and gray) matter." (PMID 21791085, 2011). "In an analysis of various tumors and tissues of the nervous system, OXCT1 enzyme activity was found to be lower in glial tumors compared to normal human brain." (PMID 21791085, 2011). "Therefore, targeting OXCT1 to increase ketone body levels to inhibit glycolysis represents a promising therapeutic strategy for glioma." (PMID 39491527, 2024). "The authors hypothesized that patients with low or very low expression of BDH1 and OXCT1 in malignant gliomas may respond better to KD therapy than patients with gliomas that express higher levels of ketolytic enzymes." (PMID 31399389, 2020). "Accordingly, a recent study showed that the expression levels of the ketone body-metabolizing enzymes succinyl-CoA 3-oxoacid CoA transferase (OXCT1) and 3-hydroxybutyrate dehydrogenase 1 (BDH1) are reduced in glioma tissue." (PMID 24728273, 2014). "The ketone body metabolizing enzymes 3-hydroxybutyrate dehydrogenase 1 and 2 (BDH1 and 2), 3-oxoacid-CoA transferase 1 (OXCT1) and acetyl-CoA acetyltransferase 1 (ACAT1) were expressed at the mRNA and protein level in all glioma cell lines." (PMID 21791085, 2011). "ECI2, MCCC2, OXCT1, SUCLG2, and CPT2 were identified as prognostic genes for glioma." (PMID 39491527, 2024). "mRNA expression of OXCT1 and BDH1 was significantly lower in gliomas compared to normal brain." (PMID 33420169, 2021).
SCOT deficiency (6 papers, 2013 to 2025). "We present a case of severe SCOT deficiency caused by a novel bi‐allelic deletion in the OXCT1 gene." (PMID 40406160, 2025). "This case presents the first known instance of severe SCOT deficiency resulting from a novel homozygous four‐exon deletion (exons 4–7) in the OXCT1 gene." (PMID 40406160, 2025). "Succinyl‐CoA: 3‐oxoacid CoA transferase (SCOT) deficiency is a rare autosomal recessive disorder caused by biallelic sequence variants in the OXCT1 gene." (PMID 40406160, 2025). "SCOT deficiency, an autosomal recessive disorder caused by bi‐allelic sequence variants in the OXCT1 gene (contains 17 exons), impairs the use of ketone bodies, leading to their accumulation and subsequent ketoacidosis." (PMID 40406160, 2025). "The OXCT1 gene is associated with SCOT deficiency and causes mitochondrial dysfunction secondary to ketone body catabolism disorder." (PMID 37377599, 2023). "At least 40 OXCT1 mutations have been reported in patients with SCOT deficiency, most of which are missense." (PMID 34765403, 2021). "Succinyl‐CoA:3‐ketoacid CoA transferase (SCOT) deficiency is an inherited metabolic disease caused by mutated OXCT1 gene resulting in recurrent ketoacidosis." (PMID 34765403, 2021). "SCOT deficiency is caused by pathogenic variants in OXCT1, resulting in the inability of extra-hepatic organs to utilize ketone bodies, and thus patients experience episodic ketoacidosis." (PMID 33415129, 2020). "However, testing the entire coding region of OXCT1 may also be performed since other mutations are known to cause SCOT deficiency in Arabs." (PMID 34765403, 2021).
diabetes (5 papers, 2004 to 2025). "In STZ + HFD diabetes mice models, hyperglycemia is also associated with reduced cardiac expression of β-hydroxybutyrate-dehydrogenase (BDH1) and succinyl-CoA:3-oxoacid CoA transferase (OXCT1) due to OGA." (PMID 35004869, 2021). "OXCT1 plays an important role in heart failure and diabetes." (PMID 38469146, 2024). "Therefore, to simulate the metabolic effect of targeting OXCT1, we exploited the chiral property of βHB by treating the cells with the metabolically inactive enantiomer S-βHB (5 mM) at a dose range of natural ketosis without causing severe ketoacidosis." (PMID 39509334, 2024).
heart failure (5 papers, 2018 to 2024). Inability of the heart to pump blood at an adequate rate to meet tissue metabolic requirements. "Research showed that the expression of ketolysis-related proteins, including BDH1 and OXCT1, was increased in patients with heart failure." (PMID 32922293, 2020). "Cardiac protection of OXCT1 knockout in TAC-induced heart failure." (PMID 35283773, 2022).
colon cancer (4 papers, 2015 to 2026). "It was found that mutating this amino acid residue to S226N abolished OXCT1's ability to inhibit the migration of colon cancer cells." (PMID 41492470, 2026). "We found that elevated OXCT1 in aggressive BCa parallels levels in patients with colon cancer and HMGCS2 loss promoting tumor progression." (PMID 39509334, 2024). "The results revealed that OXCT1 overexpression significantly impaired the migration capacity of colon cancer cells, while OXCT1 knockout significantly promoted cell migration." (PMID 41492470, 2026). "According to this guideline, colon cancers can be divided into either ketolytic (G+/K+) or glycolytic (G+/K−) subtypes based on the expression of OXCT1, ACAT1, GLUT1, and PFKPF3." (PMID 36031388, 2022). "To verify whether overexpression of OXCT1 inhibits the migratory ability of colon cancer cells via CDK8, we treated the cells with the CDK8 inhibitor (MSC2530818)." (PMID 41492470, 2026). "Taken together, OXCT1 might inhibit colon cancer metastasis by suppressing the Wnt signaling pathway." (PMID 41492470, 2026). "Next, by considering the combined biomarkers, we defined two molecular metabolism phenotypes of colon cancer: a glycolysis‐proficient phenotype (glycolysis+) with either GLUT1 or PFKFB3 overexpression and a ketolysis‐deficient (ketolysis−) phenotype by null expression of either OXCT1 or ACAT1." (PMID 36031388, 2022). "The gene expression levels of OXCT1 and ACAT1 in each colon cancer patient varied greatly, suggesting notable differences in ketolytic metabolism." (PMID 36031388, 2022). "Furthermore, although four signature molecules (OXCT1, ACAT1, GLUT1, and PFKPF3) were identified in this study to stratify the metabolic subgroups in colon cancer, they may not be the optimal set for other types of cancers." (PMID 36031388, 2022).
diabetic ketoacidosis (3 papers, 2018 to 2024). The metabolic condition resulted from uncontrolled diabetes mellitus, in which the shift of acid-base status of the body toward the acid side because of loss of base or retention of acids other than carbonic acid is accompanied by the accumulation of ketone bodies in body tissues and fluids. "Moreover, in states of sustained ketosis like diabetic ketoacidosis, the expression and activity of SCOT (encoded by the Oxct1 gene), as well as SCOT protein abundance, are diminished in the heart and skeletal muscle of rodents." (PMID 38242911, 2024). "While ketosis (outside of diabetic ketoacidosis) is not a known feature of FRDA, we reasoned that the relative deficiency of OXCT1 might elevate blood ketones in selected situations." (PMID 36016708, 2022).
liver cancer (3 papers, 2021 to 2025). An epithelial or non-epithelial malignant neoplasm that arises from the liver. "Notably, a recent study showed that extensive succinylation of LACTB K284, induced by OXCT1, inhibits LACTB activity and promotes cancer progression, implying a strong link between LACTB and liver cancer." (PMID 39047638, 2024).
lung carcinoma (3 papers, 2018 to 2025). "We also examined H1229 lung cancer cells with low expression of BDH1 and OXCT1." (PMID 29414764, 2018).
pancreatic cancer (3 papers, 2021 to 2026). "Previous studies have shown that OXCT1 was a key factor in promoting tumor progression and drug resistance in liver, lung, and pancreatic cancers, and was closely related to energy metabolism, proliferation, and survival of cancer cells." (PMID 41492470, 2026). "The protein level of OXCT1 in the other six pancreatic cancer cell lines, except for the BxPC-3 cell line, was found to be higher than that in 293T and HPDE6C7 cell lines." (PMID 34804914, 2021).
cardiac hypertrophy (2 papers, 2019 to 2022). "A recent study in cardiac hypertrophy reported SIRT3-dependent enhancement of ketone body metabolism via AMPK-mediated increase in the levels of monocarboxylic transporters 1 (MCT1) and 3-oxoacid CoA-transferase (OXCT1)." (PMID 35369299, 2022).
dementia (2 papers, 2021). Loss of intellectual abilities interfering with an individual's social and occupational functions. "Experimental evidence links OPA1 to the pathogenesis of Parkinsonian syndrome and dementia, while OXCT1 plays a central role in extrahepatic ketone body catabolism." (PMID 34683848, 2021).
diabetic cardiomyopathy (2 papers, 2024 to 2025). Diabetic cardiomyopathy is a disorder of the heart muscle in people with diabetes. "Therefore, OXCT1 may be an important diagnostic and therapeutic target for diabetic cardiomyopathy." (PMID 38469146, 2024). "We constructed a diagnostic model of DCM, and OXCT1, CACNA2D2, BCL7B, EGLN3, GABARAP, and ACADSB were potential biomarkers, which may provide new insights for improving the ability of early diagnosis and treatment of diabetic cardiomyopathy." (PMID 38469146, 2024). "We found diagnostic and predictive biomarkers of type 2 DCM consisting of OXCT1, CACNA2D2, BCL7B, EGLN3, GABARAP, and ACADSB, which may reduce the difficulty of early prediction of diabetic cardiomyopathy, and lay a foundation for prospective research." (PMID 38469146, 2024).
gastric cancer (2 papers, 2022 to 2024). A primary or metastatic malignant neoplasm involving the stomach. "The gastric cancer tissues and cell lines exhibited downregulated circ-OXCT1, which was shown to be substantially correlated with lymph node metastasis, pathologic stage, and overall survival rate." (PMID 38505309, 2024).
Hyperglycemia (2 papers, 2021 to 2024). An increased concentration of glucose in the blood. "Studies have shown that hyperglycemia reduces the expression of Bdh1 and Oxct1 in the hearts of mice." (PMID 38469146, 2024).
malignant glioma (2 papers, 2013 to 2018). A grade III or grade IV glioma arising from the central nervous system. "They hypothesized that patients with low or very low expression of BDH1 and OXCT1 in malignant gliomas may respond better to KD therapy." (PMID 29414764, 2018). "It seems reasonable to hypothesize that patients with low or very low expression of key ketolytic enzymes (e.g., OXCT1, BDH1) in their malignant gliomas may respond better to the KD therapy than those patients with positive expression of these enzymes." (PMID 23829383, 2013).
prostate carcinoma (2 papers, 2017 to 2021). A carcinoma that arises from epithelial cells of the prostate gland. "OXCT1 expression is increased in LNCaP-SF cells, an androgen-independent LNCaP cell line derivative, as well as in high-grade prostate cancers relative to normal and low-grade samples." (PMID 34680521, 2021). "As is the case in androgen-independent cell lines, OXCT1 is thought to contribute to the metabolic processing involved in the development of advanced prostate cancer stages." (PMID 34680521, 2021). "TUFM and ACPP, which are frequently associated with prostate cancer, and two metabolic enzymes, LDHB and OXCT1, were further confirmed at the protein level in DHT (androgen)- and FSK (PKA signaling)-stimulated VCaP cells by immunoblotting." (PMID 34680521, 2021).
sarcopenia (2 papers, 2024 to 2025). Progressive decline in muscle mass due to aging which results in decreased functional capacity of muscles. "Some studies have demonstrated that pimozide can inhibit skeletal muscle ketone oxidation via SCOT/Oxct1, thereby may attenuating sarcopenia." (PMID 38962732, 2024).
Alzheimer disease (1 paper, 2025). A progressive, neurodegenerative disease characterized by loss of function and death of nerve cells in several areas of the brain leading to loss of cognitive function such as memory and language. "Investigators also performed a cis-MR analysis using only variants in the OXCT1 gene region, which did not provide evidence of beneficial effects on cognitive performance or Alzheimer’s disease." (PMID 40488801, 2025).
anaplastic gliomas (1 paper, 2013). "The rate limiting mitochondrial ketolytic enzymes (OXCT1 and BDH1) were either LOW or VLOW, concordantly in 14 of the 17 GBMs and in 1 of 5 anaplastic gliomas, whereas at least one of the glycolytic enzymes was POS in 13 of these 17 GBMs and all 5 anaplastic gliomas." (PMID 23829383, 2013).
bladder tumors (1 paper, 2024). "In the context of gemcitabine, the 5637GR bladder tumors had elevated expression of the OVOL1 target genes, including SOX2 and SOX9, in a OXCT1-dependent manner, resulting in greater mitotic index." (PMID 39509334, 2024).
cardiomyopathy (1 paper, 2025). A disease of the heart muscle or myocardium proper. "Interestingly, changes in FGF21-responsive genes such as OXCT1, the SUCL complex, PDHA1, OGDH, ACO2, IDH3B, and ETC components (MT-CO2, COQ9, UQCRQ, SDHB/D and NDUFB7) are linked to mitochondrial deficiency syndromes manifesting cardiomyopathy and encephalopathy." (PMID 40998786, 2025).
Cognitive impairment (1 paper, 2023). Abnormal cognition is characterized by deficits in thinking, reasoning, or remembering. "Cis-MR showed little evidence of therapeutic modulation of OXCT1 on cognitive impairment." (PMID 37667256, 2023).